IL10 (interleukin 10)
Diseases named in the same sentence as IL10 in open-access papers (continued):
Sharing a sentence is not in itself a finding about the gene and the disease.
infection (continued). "mRNA IL-27p28 transcripts are increased in the lungs during infection and IL-27 signaling promoted the generation of IL-10 secreting virus-specific CD8 T cells." (PMID 38966644, 2024). "IL-10 overexpression reduces vaccine efficacy in transgenic mice, accompanied by higher levels of infection in the liver and iNOS expression." (PMID 39199857, 2024). "One mechanism that Staphylococcus aureus biofilm elicits in the host to facilitate infection persistence is the production of the anti-inflammatory cytokine interleukin-10 (IL-10)." (PMID 38179975, 2024). "Il10 helps to maintain tissue homeostasis during severe infection in kidney disease by inhibiting excessive inflammatory responses and promoting tissue repair." (PMID 39064752, 2024). "It has been documented that endogenously produced IL-10 plays a significant role in the establishment and maintenance of infections by intracellular pathogens, including viruses." (PMID 39199857, 2024). "The cytokine IL-10 is a crucial regulatory cytokine and mediator of anti-inflammatory processes that safeguard a host against exaggerated reactions to infections." (PMID 38724594, 2024). "IL-10+ B cells are critical for immune homeostasis and restraining immune responses in infection, cancer, and inflammation; however, the signals that govern IL-10+ B cell differentiation are ill-defined." (PMID 38182585, 2024). "The role of IL-10 in fostering a SA–host relationship is well-documented in both the clinical and mouse literature on SA colonization and infection dynamics." (PMID 38786139, 2024). "In a recent study, the steep increase in the expression of the proinflammatory cytokines IL-6, IL-8, and IFN-γ and that of a regulator cytokine, IL-10, was detected at 5 h after infection." (PMID 38787238, 2024). "In the untreated infected group (G2), IFN-γ expression at 6th days post-infection (pi) was 2.12 ± 0.97, and IL-10 levels were measured at 1.81 ± 0.64 on the same day pi." (PMID 39421828, 2024). "In accord, we observed increased Il-10, Cd4, Cd8a, and Foxp3 mRNAs in our RNA-seq data from K-RasLA1 mice on day 7 post-infection." (PMID 39338937, 2024). "In contrast, IL-10 down-regulated in feedback to infection of the A549 cell line with sensitive [P=0.002; P=0.004]; INHR [P=0.02; P=0.007]; RifR [p=0.2; P=0.01]; MDR [P=0.01; P=0.004]; XDR [p=0.1; P=0.004] Mtb strains 24 and 48 hr post-infection, respectively." (PMID 38800030, 2024). "The mice treated with cambinol at 7 d post-infection displayed a lower serum level of IL-10 (3.660 ± 0.803 pg/mL vs. 5.930 ± 0.797 pg/mL)." (PMID 39770737, 2024). "It is found that IL‐10 exhibits inhibition of antibody response in bladder impairment during infection." (PMID 39723046, 2024). "Interleukin-10 (IL-10) plays a dual role by modulating the inflammatory immune response during infection and preventing damage during pregnancy." (PMID 39199857, 2024). "Conversely, IL-10 was minimally produced by HBV-specific T-cells of patients with resolved infection whereas it was most pronounced in CHB patients followed by both IT and IC." (PMID 39445017, 2024). "On the other hand, Leishmania is capable of directing the response to the Th2 profile, characterized by the production of IL-10 and IL-4 cytokines, which inhibit macrophages and lead to proliferation and resistance to infection." (PMID 38312642, 2024). "Interleukin-10 (IL-10) is a cytokine known for its anti-inflammatory properties, crucial for immunoregulation during infection." (PMID 38831352, 2024). "The content of IL-10 in the lung was the highest on the fourth day after infection, and the content of IL-10 in intestinal tissues was the highest on the third day after infection, with significant differences (P < 0.01)." (PMID 38727214, 2024). "At the same time, secondary infections displayed lower levels of IL-6 and IL-10 during Ph II compared to primary DENV infections." (PMID 39457019, 2024).
infection (continued). "Previous studies have suggested that MDSCs are the main producers of IL-10 in tumors and infections." (PMID 39035356, 2024). "At day 6 post-infection when most of the inflammation had resolved in control animals, lesions in the anti-IL-10 treated animals still had significant 18FDG uptake and some lesions had increased in intensity from that observed at day 2 post-infection." (PMID 38950078, 2024). "When this vaccine was administered in combination with an anti–IL-10 blocking antibody, bacterial burden at the site of infection was further diminished as early as day 3 after infection." (PMID 38973612, 2024). "We also assessed the differences between circulating levels of IL-10 depending on the presence of single or mixed infection with two investigated pathogens, detected by PCR." (PMID 39770719, 2024). "Upon infection, there was an enhanced level of IL-12 expression noted in MDSCs whereas the IL-10 level decreased." (PMID 39452748, 2024). "They found elevated serum levels of IL-10 in mice after experimental infection with a virulent strain of E. muris at day 8 post-infection, and the production of high levels of the cytokine was mainly due to IL-10-producing lymphocytes and was antigen-specific." (PMID 39770719, 2024). "It is important to note that while macrophages in IL-10-tg mice exhibit elevated IL-10 expression, they are reported to remain fully immunocompetent, mounting an appropriate immune response post-infection." (PMID 39199857, 2024). "T cell–associated cytokines IL-17 and IL-22 were significantly increased in mice immunized with vaccine + anti–IL-10 when compared with control groups, and production was also sustained up to day 10 after infection." (PMID 38973612, 2024). "Plasma fibrinogen levels were higher in the anti-IL-10 treated animals compared to controls at days 2–10 post-infection, suggestive of increased coagulation." (PMID 38950078, 2024). "Our data show that IL-10 limits the magnitude of the effector T cell clonal burst during the acute phase of infection." (PMID 38950078, 2024). "As a surrogate of host response to infection with H. diminuta, infected mice showed increased concanavalin-A (con-A) stimulated splenic production of IL-4, IL-10, and IL-13, the variability in the data reflecting the individual mouse’s response to the worm." (PMID 39083533, 2024). "During the chronic infection stage, F. gigantica promotes the secretion of IL-10 and TGF-β through the release of FgESP, which induces a low-responsive immune state that limits tissue damage and facilitates ongoing infection by flukes." (PMID 39696651, 2024). "In our infection model of myeloid STAT3 deficiency, autocrine IL-10 is most likely the major component of the defective inflammation loop leading to the hyperinflammatory macrophage phenotype." (PMID 37982695, 2024). "In pediatric hematology patients, IL-6 and IL-10 have a good predictive value for the diagnosis of serious infections." (PMID 39559703, 2024). "Infection with helminths induces polarized type 2 immunity characterized by elevated expression of cytokines, including IL-4, IL-5, IL-10, and IL-13." (PMID 38166140, 2024). "In the infected untreated group (G2), IL-10 expression appeared on the 6th day post-infection, with a level of 1.81 ± 0.64." (PMID 39421828, 2024). "In contrast, higher CCI, age at infection, viral load, respiratory IL-10, and respiratory rate at triage were the drivers of worse clinical outcome." (PMID 39633683, 2024). "In contrast, a Th2 type response, marked by elevated levels of IL-10 and TGF-β, is associated with susceptibility to infection, disease progression, parasite replication and persistence." (PMID 39192975, 2024). "Infection with CHIKV also increased the levels of inflammatory cytokines and chemokines (TNF-α, IL-6, IL-10, and CCL-2), which are associated with severity, morbidity, and mortality in patients." (PMID 39339151, 2024).
infection (continued). "The IFN-γ/IL-10 ratio was shown to be 1.679 and 18.139 at 7 and 14 d post-infection, respectively, which is suggestive of favoring Th1 immune responses." (PMID 39770737, 2024). "CD4 T cell polyfunctionality index was lowest in Bhlhe40-/- mice and highest in Il10-/- mice, and these indices reversely correlated with bacterial shedding over the course of C. muridarum primary infection." (PMID 38271477, 2024). "We observed that in late presenters, IFN-ɣ, IL-6 and IL-10 levels were high and correlated with other markers of infection." (PMID 38992229, 2024). "While IL-6 decreases quickly in the first 12 h from the onset of the blood infection, IL-10 tends to persist for longer during the septic state and performs as a valuable diagnostic biomarker." (PMID 38254697, 2024). "IL-10 thus reflects the anti-inflammatory response to postoperative infection and surgical injury, which contributes to postoperative complications such as AL." (PMID 38696304, 2024). "Interleukin-10 (IL-10) is an anti-inflammatory cytokine that limits immune responses to pathogens, preventing host damage; moreover, it plays a core role in infection control as a broad-spectrum, anti-inflammatory agent." (PMID 39770849, 2024). "Both the immunization and enteric phase + immunization groups had higher concentrations of serum IL-4 and IL-10 than the control, and the infection increased IL-4 and IL-10 levels related to the immunization group." (PMID 39066367, 2024). "On the contrary, Treg cells, generally enriched in the late stage of infection, promote the self-renewal of ISCs through IL-10, to supplement ISCs which are reduced in early infection." (PMID 39872442, 2024). "On the other hand, neutralizing antibodies significantly downregulated infection-induced IL-10 (54.9% reduction compared to infected cells, p < 0.0001, F = 28.47)." (PMID 38750790, 2024). "On the contrary, the transcription of il-6 (pro-inflammatory gene) and il-10 (anti-inflammatory gene) was significantly up-regulated in response to infection with any of the viruses." (PMID 38921776, 2024). "Follow-up studies are needed to compare prior infection versus colonization and their impact on IL-10 production and immune imprinting." (PMID 39680461, 2024). "In the S. Tm group, infection caused significant increases in TNF-α, IL-10, IL-22, and IFN-γ levels by 150.6%, 105.4%, 49.8%, and 103.4%, respectively, compared to the uninfected controls." (PMID 39456424, 2024). "At 24 h post infection in 31 human lung explant tissue samples, key cytokines such as interleukin (IL)-6, IL-10, tumor necrosis factor-alpha (TNF-α), and interferon-gamma (IFN-γ) were upregulated." (PMID 39456722, 2024). "In contrast, IL-6 levels were significantly elevated in colon tissues from mice treated for translocated infection, while IL-10 expression remained unchanged across all groups." (PMID 39664059, 2024). "Noteworthy, similar to the previous analyses, the profile of IL-6 and IL-10 cytokines show the greatest changes during infection, especially when the infection occurs in the 1st gestational trimester." (PMID 39495782, 2024). "Flow cytometry analysis revealed that CD4+, CD8+, and γδ+ T cell subsets all contributed to both IL-17 and IL-22 production on day 3 after infection, and the inhibition of IL-10 significantly enhanced the production of these cytokines by all T cell subsets." (PMID 38973612, 2024). "Murine studies have also shown IL-10 blockade after infection can improve memory Th17 responses against S. aureus infection." (PMID 38973612, 2024). "A major finding of this study is that during the first 24 hours of infection, GC colonization elevates the local secretion of the antiinflammatory cytokine IL-10 at the cervix." (PMID 39585777, 2024). "An additional benefit of linking IL-10 to anti-SA immune imprints is the potential to deliver abundant IL-10 to promote SA survival at sites of colonization or infection, through IL-10’s broad innate immune suppressive functions." (PMID 39681568, 2024).
infection (continued). "A balance between TNF-α and IL-10 concentrations is crucial for controlling infection within a single granuloma." (PMID 39650648, 2024). "The observation of higher levels of IL-10 is in line with earlier studies, which already described a correlation between its increase and worse outcomes of infection." (PMID 38543749, 2024). "The increase in TGF‐β and IL‐10 contents in intestinal tissue after ETEC infection is a protective mechanism against infection and the subsequent inflammatory response." (PMID 39351242, 2024). "In vivo, reduced IL-10+ M-MDSCs were observed in the lungs of Dectin-1KO mice after 72 h and 2 weeks of infection, while PMN-MDSCs presented impairments in IL-10 expression 2 weeks post-infection." (PMID 39035356, 2024). "Research has demonstrated that infection of wild-type mice with L. monocytogenes leads to elevated levels of blood IL-10 levels 3–4 days after infection, which aligns with the findings of this study." (PMID 39057985, 2024). "A Zimbabwean study assessing the cytokine response to AWA stimulation of PBMCs revealed that IL-10 was most strongly correlated with Sh infection intensity, and that participants with high intensity infection also tended to produce lower IL-5 levels." (PMID 39250522, 2024). "In an in vitro study with human macrophages, infection with Mycobacterium bovis bacillus Calmette–Guérin (BCG) induced the inhibition of CTSS with IL-10 and consequently reduced MHC class II antigen presentation." (PMID 38668343, 2024). "The key finding is that IL-6 and IL-10 levels rise earlier in secondary infections compared to primary infections, whereas elevated cytokine levels typically occur later in the febrile phase." (PMID 39457019, 2024). "We observed increases in IL4 and IL10 transcription at early infection times (24-48 HPI) in the mesenteric lymph nodes." (PMID 38511816, 2024). "In KO THP-1dM cells, Lt-P10 infection induced a significant increase of IL-10 (p = 0.02) and a significant reduction of IL-2 (p = 0.03); TGF-β production was only marginally modified." (PMID 38707903, 2024). "In the present study, the three dietary-supplemented groups with UROEE, CsNPs and UROEE-CsNPs showed that the mRNA expression level of IL-10 was significantly decreased following primary and secondary infection, when compared to NC group." (PMID 38492183, 2024). "During the initial phase of infection, we detected elevated levels of IL-10 in mice that received mAb 1B5 and 8E6." (PMID 39460288, 2024). "These markers were better than plasma cytokine levels (such as CXCL10, IL-10) for differentiating MIS-C from infection controls." (PMID 38762592, 2024). "The excessive secretion of IL-6 and IL-10 indicates an early imbalance between pro- and anti-inflammatory res­ponses in patients with infection." (PMID 39212218, 2024). "S. aureus induces IL-10, which impedes effector T cell responses, facilitating persistence during both colonization and infection." (PMID 38973612, 2024). "Both the immunization and muscular phase + immunization groups had higher concentrations of serum IL-4 than the control, and the infection increased IL-4 and IL-10 levels related to the immunization group." (PMID 39066367, 2024). "Instead, they develop late after infection, which makes sense because lung MDSCs produce IL-10 that can impede neutrophil recruitment if produced too early." (PMID 38397917, 2024). "Despite the fact that strong inflammatory responses are observed during T. parva infection, the production of anti-inflammatory cytokines and especially IL-10 have also been described as a potentially protective measure against lethal infection." (PMID 38803499, 2024). "Whole body 18FDG-PET-CT imaging showed that IFNγ promotes SARS-CoV-2 induced pulmonary disease and IL-10 dampens the size, activity, and duration of lung lesions induced after infection." (PMID 38950078, 2024).
infection (continued). "Second, the D37712 and D23580 strains stimulate similar levels of up-regulation of IL10 gene expression upon infection of human dendritic cells." (PMID 38623411, 2024). "Using preclinical models, we demonstrate for the first time to our knowledge that the transient inhibition of IL-10 during immunization improves vaccine-induced T cell responses that lead to more effective clearance of infection." (PMID 38973612, 2024). "Further studies are needed to clarify the mechanism of IL-10 involvement in IgG synthesis during the infection with E. canis and A. phagocytophilum." (PMID 39770719, 2024). "The expression of IL-10 and IL-8 in spleen, anterior kidney, and brain tissue were up-regulated at different time points after infection." (PMID 38473757, 2024). "The regulatory functions of IL-27 include inhibition of Th2 and Th17 cell differentiation, and the induction of IL-10-producing Type 1 regulatory cells (Tr1) cells controlling immunopathology in the setting of infection." (PMID 38966644, 2024). "The sudden increase of IL-12 producing macrophages at 12 h post-infection suggested that macrophages were trying to combat infection; nonetheless, their population subsided at 18 h due to overexpression of IL-10 by the majority of the population." (PMID 38299832, 2024). "The mice showed elevated splenic IL-10 at 11 dpi, supporting published literature that germ free mice display elevated type 2 cytokines in response to infection with H. diminuta." (PMID 39083533, 2024). "During the initial infection, EBV uses the viral IL-10 (vIL-10) encoded by the lytic gene BCRF to mimic human IL-10 and suppress the secretion of IL-2 and IFN-γ." (PMID 38675906, 2024). "As highlighted here, it is known that IL-10 acts as a potent suppressor of pro-inflammatory cytokine production by immune cells, thus attenuating immune response during infection and reducing inflammation." (PMID 38251210, 2024). "IL-10 itself is critical for suppressing excessive activation of the immune response during infection, limiting host damage." (PMID 39132450, 2024). "In the chronic phase of infection, the Th2 response is controlled by anti-inflammatory measures including IL-10, Tregs, and alternatively activated macrophages (AAM)." (PMID 39329761, 2024). "A distinct cytokine profile (severe elevation in interferon-γ and IL-10 with a modest elevation in IL-6) in children helps differentiate HLH from infection." (PMID 39398688, 2024). "Anti-inflammatory cytokine IL-10 levels increased with infection, but significantly decreased in the serum of Baf A1 treated-mice at 30 dpi." (PMID 39497817, 2024). "B. abortus 2308 infection induced a decrease in peripheral IL-10 concentration in the Ba group mice when compared to the Ctr group (p < 0.001)." (PMID 38794208, 2024). "For example, our previous studies show that viral infection induces type I interferon signaling, which significantly upregulates the expression levels of cytokines such as IL-10 and induces persistent host infection." (PMID 39054472, 2024). "Taken together, ITA and its isomers MES and CTC have an overall similar immunomodulatory effect on production of the cytokines IL6, TNFα, IL1β and IL10 in response to infection with C. burnetii." (PMID 39156902, 2024). "While type-1 T-cells induce IL-6, IL-1β, TNF-α, and IL-12 production by monocytes/macrophages to fight the infection, type-2 T-cells are associated with a regulatory phenotype (IL-10 and TGF-β) and successful infection establishment." (PMID 39192975, 2024). "T helper 2 cells can produce cytokines, including IL-4, IL-5, IL-10, and IL-3,27 and the response of these cells plays a central role in protection against infection." (PMID 39807418, 2024). "IL-10 is produced by numerous immune cells during infection (e.g., macrophages, T cells, and neutrophils)." (PMID 39650648, 2024). "Upon SA infection, IL-10 is abundantly produced and can drive host protection or pathology depending on the site of infection." (PMID 39681568, 2024).